VIM (vimentin)
Diseases named in the same sentence as VIM in open-access papers (continued):
Sharing a sentence is not in itself a finding about the gene and the disease.
tumor (continued). "In addition, tumor cells exhibited elevated ITGA5 and VIM levels and reduced integrin β1 (ITGB1) and CDH1 levels after suspended coculture with CAFs in MUs, thus indicating that interaction with CAFs in MUs could further maintain the ITGA5high mesenchymal phenotype in ATCs." (PMID 30710055, 2019). "However, immunoblotting analysis of CRC tumor microenvironment cultures (HCT116 and HCT116R) treated with resveratrol alone or in combination with 5-FU or with TNF-β or with TNF-α showed marked suppression of vimentin, the transcription factor slug and induction of E-cadherin expression." (PMID 30002278, 2018). "As our in vitro studies revealed expression changes of mesenchymal proteins, SNAIL and vimentin, and of MMP-2 and MMP-9 on cancer cells treated with the combination of metformin and selumetinib, we also investigated whether the combination therapy blocks tumour metastatic behavior in vivo." (PMID 26673006, 2016). "Also Vimentin was negative, so excluding a mesenchymal derivation of the tumour." (PMID 26925281, 2016). "First, we studied the expression of EMT markers vimentin, fibronectin, N-cadherin and E-cadherin in a set of 23 radical prostatectomy (RP) specimens to determine which marker is most representative for EMT in clinical specimens and whether EMT markers were co-expressed within the same tumor areas." (PMID 26041890, 2015). "However no sorted tumor cells (CK+ and/or vimentin+, CD45- cells) were observed." (PMID 24886394, 2014). "Despite repeated stainings with vimentin, no clear tumor evaluation could be made due to artifacts." (PMID 23662242, 2013). "Importantly, upon bevacizumab treatment single tumor cells invading the brain parenchyma could be readily identified (GBM10 cells were identified using an antibody that recognizes human but not mouse vimentin)." (PMID 23457577, 2013). "Interestingly, the patient tumor, as well as xenografts, expressed CK18, an epithelial marker, and vimentin, a mesenchymal marker, with the stromal portion of the patient tumor, but not the xenograft, also staining positively with the anti-human vimentin antibody." (PMID 24324581, 2013). "Interestingly, tumor tissues recovered from the mouse xenografts also displayed increased N-cadherin and Vimentin expression in the Kindlin-2 overexpressing tumors, with no changes for N-cadherin and Vimentin in Kindlin-1 overexpressed or the control tumors." (PMID 23209705, 2012). "No false positive result was seen in blood from tumour-free control mice (n = 20), proving that the used PCR primers were specific to human sequences and therefore did not give any background signals, for example for Vimentin that would be expected in mesenchymal blood cells." (PMID 22591372, 2012). "Interestingly, the tumor cells were largely devoid of epithelial markers, Epcam and cytokeratins, but strongly expressed vimentin, indicating that in non-transgenic mice transition into the mesenchymal state is favored, possibly as a consequence of an interaction with the host immune system." (PMID 20730114, 2010). "However, adding vimentin to basal cytokeratins compilation (vimentin or CK5/6 or CK14 or CK17-positive vs. negative tumours) could significantly determine the prognosis." (PMID 19695088, 2009). "Malignant tumor cells were identified as mesenchymal cells based on their negative immunolabeling for cytokeratin A1/AE3 and their positive vimentin immunoreaction, together with the lack of expression of the MEC markers cytokeratin 14 and p63." (PMID 40509039, 2025). "Immunohistochemical analysis demonstrated positive expression of CK, vimentin, and CD34 in tumor cells, with negative immunoreactivity for INSM1, S100, and CD68—findings consistent with the established pathological diagnostic criteria for ES." (PMID 41244767, 2025). "The tumor was histologically composed of oncocytic cells that expressed KRT7, vimentin, SDHA, SDHB and fumarate hydratase, but not KIT, GATA3 and alpha-methylacyl-CoA racemase." (PMID 39980061, 2025).
tumor (continued). "The tumor cells tested negative for CD117, anaplastic lymphoma kinase, and pan-cytokeratin and positive for smooth muscle actin, vimentin, and desmin." (PMID 40761993, 2025). "Pathologically, meningiomas are composed of lobulated tumor cells, often arranged in a “whorled” pattern, and immunohistochemically positive for EMA and Vimentin, but negative for S100." (PMID 40046675, 2025). "Our analyses suggest that the three markers, VIM, TMEM220, and PPM1 N, exhibit significantly higher methylation levels in urinary tumor DNA (utDNA) relative to non-cancer specimens." (PMID 40234942, 2025). "Immunohistochemical staining showed the tumor cells to be negative for Epithelial Membrane Antigen (EMA), positive for Vimentin (++), D2-40 (++), and negative for Progesterone Receptor (PR)." (PMID 40018446, 2025). "The top negative DEGs, including ABCB1, SPRY1, EREG, PIK3R1, SPTBN1, VIM, KDR, and others, exhibit a negative correlation with tumor purity while demonstrating a strong positive correlation with T‐cell infiltration, especially CD8+ T cells." (PMID 40567015, 2025). "Even though specific immunohistochemical markers for DFSP are lacking, the tumour cells typically demonstrate positivity for CD34 and vimentin on immunohistochemistry analysis." (PMID 40556795, 2025). "In our case, the tumor cells demonstrated positivity for p40, CK5/6, and cytoplasmic vimentin expression with membranous accentuation but lacked muscle-specific markers." (PMID 39677213, 2024). "Immunohistochemically, the tumor cells exhibit positive CD56 (NCAM) expression and are negative for S100 protein and vimentin." (PMID 38672619, 2024). "Immunohistochemically, the tumor cells were positive for CD68 and vimentin, but were negative for epithelial membrane antigen, cytokeratin, and additional muscle markers." (PMID 38515205, 2024). "The non-epithelial characteristics of this tumor were demonstrated by the immunohistochemical results, which were negative for AE1/3 and CK5/6 and positive for vimentin and SATB2." (PMID 39568569, 2024). "Immunohistochemistry revealed that the tumor cells were positive for α-smooth muscle actin (SMA) and vimentin, and negative for S100, CD34, and desmin." (PMID 39130873, 2024). "Histopathology revealed a cellular tumor comprising tightly packed round to fusiform cells arranged around blood vessels with intervening thick collagen, positive for CD99, vimentin, BCL2, CD34, and STAT6 and negative for EMA, CK AE1/AE3, S100, TLE1, and SMA." (PMID 38606238, 2024). "Immunostaining revealed that GPx2 KD tumours contained carcinoma areas that were KRT14, N-CAD, VIM positive and E-CAD negative as compared to control tumours, indicative of binary EMT." (PMID 38238426, 2024). "Immunohistochemical stains were positive for PAX8, AE1/AE3, E-cadherin, CD10, and vimentin; the tumor was negative for CK7, CD117, racemase, ALK, and HMB45; the tumor showed focal, scattered staining for Melan-A and very weak cytoplasmic staining for CAIX." (PMID 39561576, 2024). "In this report, nearly all tumor cells were positive for GATA-3, KRT7, EMA, E-Cadherin, Ksp-Cadherin, 34βE12, and AMACR in varying intensities, focally positive for CD10 and Vimentin, while negative for CD117, TFE3, RCC, and CAIX." (PMID 37143937, 2023). "The ZEB1 knock-out in M13HS tumor cells was not correlated with the down-regulation of the EMT-related markers N-CADHERIN (CDH2) and VIMENTIN and up-regulation of miR-200c-3p." (PMID 38139138, 2023). "Once again, our results suggested that spheroids were composed of only tumor cells, as nearly all cells in spheroids were positive for PAX8 and negative for vimentin." (PMID 36875739, 2023). "Snaillo tumours displayed a partial EMT in vivo, with reduced membranous E-cadherin but no increased vimentin on histology." (PMID 36788501, 2023). "IHC stain of CD8+ TILs, tumor-infiltrating FOXP3+ Tregs, E-cadherin score, and vimentin score was not different between these two groups." (PMID 37340370, 2023).
tumor (continued). "Immunohistochemically, tumour cells were diffusely positive for CD10, EMA, and vimentin, and negative for CK7, TTF-1, renal cell antigen, and E-cadherin." (PMID 36900135, 2023). "Recent evidence on the role of vimentin in LSCC has shown that vimentin plays an important negative prognostic role in LSCC, regardless of the TNM stage and histological grade of the tumor." (PMID 36833374, 2023). "The tumour cells express SMA and vimentin; partially express desmin, CD34, CD68 and ALK; and do not express CK or S100." (PMID 36855132, 2023). "The antitumour efficacy of bispecific antibodies plus talazoparib was not improved in the tumours that were insensitive to EGFR blockade, corresponding to the high expression of VIM and FN1 genes and relatively low expression of CDH1 and CLDN7 genes." (PMID 37441599, 2023). "Cit-vimentin, but not native-vimentin, stimulated ACPA+ RA CD8+ T cells significantly killed DLD-1 tumor cells." (PMID 36658110, 2023). "Microscopic examination revealed that the tumor was spindle cell sarcoma, which was diffusely expressed of CD34, vimentin, S-100, and Pan-TRK, but negative for SOX10, EMA, SSTR2, PR, and STAT6." (PMID 35572973, 2022). "After carefully reviewing the histologic morphology in our present case, we have found ~10% of tumor cells showing clear cytoplasm, but all tumor cells stained consistently for S100, alpha-inhibin, NSE, Vimentin, and negative for CD10 and CA9." (PMID 35220972, 2022). "Markers vimentin, synaptophysin, MENA, ECAD and CK20 had lower expression in the tumour tissue relative to that in the non-tumour tissue with the exception of MENA for one patient and CK20 for another patient." (PMID 36362433, 2022). "Cells from Grade 4 tumour showed heterogenous expression of CK8, with some cells strongly positive and some cells not expressing CK8, while vimentin expression decreased in all cells compared to cells grown from lower grade samples." (PMID 35102500, 2022). "Immunohistochemical staining of the tumour was positive for Renin, CD34, Vimentin, and synaptophysin (Syn) and negative for somatostatin receptor 2 (SSTR2) and chromogranin A (CgA)." (PMID 35303838, 2022). "The immunoreactivity for pan-keratin, vimentin, CD34 and PCNA was positive, but INI-1 was negative in the organoids similar to the original EPS tumor tissue and xenograft tumors." (PMID 35677170, 2022). "At immunohistochemical examination, tumor cells stained negative for CK7, CD10 and RCC and positive for both WT1 (nuclear, intense) and vimentin (cytoplasmic, intense, and diffuse)." (PMID 35198098, 2022). "Tumor grade progression was closely correlated with LVI (p = 0.0338), expression of vimentin (p = 0.000), tumor budding (p = 0.000), and lack of E-cadherin (p = 0.0028)." (PMID 36143062, 2022). "In this case, the IHC staining results suggested that the patient’s tumor was diffusely positive for CD117, vimentin, CD56 and NSE and focally positive for desmin, negative for other markers, and had a ki-67 level of ~ 40%." (PMID 35488288, 2022). "Vimentin staining is indicative of epithelial to mesenchymal transition (EMT) and was evident in the tumour regions, while excluded from the glands that maintained normal architecture." (PMID 36075907, 2022). "The immunoreactivity for pan-keratin, vimentin, CD34 and PCNA was positive, but INI-1 was negative in the ODX1 and ODX2 tumors similar to the original EPS tumor tissue." (PMID 35677170, 2022).
tumor (continued). "Reduction of the mesenchymal marker vimentin, upregulated by TGF-β1, and restoration of the epithelial marker E-cadherin, reduced by TGF-β1, were detected in both tumor cell lines in the presence of Zn-nonoate." (PMID 36077778, 2022). "We found that PDGFRβ, PKCα, FRA1, and VIM were readily detected in ER− and BRCA1 weak or non-detectable tumor cells, whereas these proteins were barely detectable in ER+ and BRCA1+ tumor cells." (PMID 33478572, 2021). "Immunohistochemical staining indicated the tumour was positive for CD34, STAT6, vimentin and bcl-2, but negative for cytokeratins, D2-40 and S-100." (PMID 33623662, 2021). "Immunohistochemical examination showed that the tumor cells were positive for both epithelial (cytokeratin AE1/AE3) and mesenchymal cell markers (vimentin); however, they were negative for integrase interactor 1 (INI1)." (PMID 33903966, 2021). "Upon immunohistochemistry, these tumor cells expressed Ca19-9 and CK7, while staining negative for vimentin and Pax-8, thereby representing PDAC." (PMID 34059139, 2021). "The tumor showed focal CK7 positivity in individual cells, and was CD117 positive, CD10 positive and vimentin negative." (PMID 34680535, 2021). "In one case, tumor cells turned out to be negative with both CK7 and CK20, whereas vimentin was expressed with a distinct perinuclear dot-like pattern." (PMID 34359794, 2021). "The healthy control slides were negative for the tumour markers (CK/EpCAM, PAX8 and vimentin), but a few WBCs showed co-expression of PD-L1 and CD16/45." (PMID 34944844, 2021). "In our case, we found that the tumor specimen was positive for CK, CK7, P63, and vimentin, but negative for EMA, TTF-1, smooth muscle actin, desmin, carletinin, and D2-40." (PMID 34766593, 2021). "Above data imply that the negative correlation between miR-146a and vimentin affects ESCC tumorigenesis and tumor progression, both in vitro and in ESCC patient specimens." (PMID 33248456, 2020). "Immunohistochemistry (IHC) showed that, in CDX and two PTs, tumor cells were positive for EpCAM and CK8/18 and negative for CK7 and vimentin." (PMID 32313004, 2020). "We detected β-catenin positivity in OPSCC cells, whereas vimentin expression was solely seen in OPSCC-related stromal tissue and not in tumor cells." (PMID 32794417, 2020). "Furthermore, staining for vimentin, another mesenchymal marker, showed a lack of expression within the epithelial component of the normal-appearing mucosa [SB474N], but a slight increase within the epithelial compartment upon loss of KLF4 in the tumor tissues [SB474T, white arrowheads]." (PMID 32566755, 2019). "Immunohistochemically, the tumor cells were positive for hepatocyte paraffin 1, AE1/AE3, and CD10 and negative for AFP, progesterone receptor, vimentin, chromogranin A, and synaptophysin." (PMID 31784920, 2019). "Tumor cells show a strong positive reactivity for CK7 and EMA with negative reaction for CD10 and vimentin in IHC study, although the reported case was CD10 positive." (PMID 30794153, 2019). "Immunohistochemistry demonstrated that the tumor cells were positive for CD34, STAT6, vimentin, and Bcl-2, and negative for α-SMA, S100, and EMA." (PMID 31687030, 2019). "Based on immunohistochemical examination, the tumour cells were positive for CD34, Bcl2, vimentin, and CD99 and negative for desmin and S-100." (PMID 31391089, 2019).
tumor (continued). "Immunohistochemical staining showed that the tumor cells were negative for AE1/AE3, CK18, CK7, CK19, Hepatocyte Paraffin-1, Glypican-3, Arginase-1, CD56, Chromogranin A, Synaptophysin, Vimentin, and Carcinoembryonic antigen." (PMID 31488173, 2019). "Compared to the total tumor population, CD105+ CSC clone expressed the stem cell related genes Musashi (MSI), Vimentin (VIM) and OCT4-A, and lacked the expression of the epithelial marker E-CAD." (PMID 29854307, 2018). "A liquid biopsy of circulating tumor cells (CTCs) was also performed, and EMT-CTCs positive for vimentin but negative for ALK rearrangement were detected per 7.5 ml blood by FISH." (PMID 29844868, 2018). "The tumor cells were diffusely positive for AFP, CK, CK8/18, GPC-3, and hepatocyte, but negative for CD30, CD34, CK19, D2–40, PLAP, and vimentin." (PMID 29351804, 2018). "Immunohistochemical staining showed that the tumor cells were positive for CK, CK8/18, AFP, hepatocyte, GCP3, but negative for PLAP, CD10, CD30, CD34, and vimentin." (PMID 29351804, 2018). "Singh K showed that the tumor cells are positive for calcitonin, HMB-45, carcinoembryonic antigen (CEA), syn, chromogranin, vimentin, and epithelial membrane antigen and negative for TG, S-100, melan A, and TTF-1." (PMID 30424779, 2018). "MMDSCs but not gMDSCs show strong affinity towards the tumour cells and induce EMT phenotype (elongated spindle-shaped morphology), which was confirmed by strong Vimentin and CK14 expressions, established markers of EMT phenotype and invasion." (PMID 28382931, 2017). "Immunohistochemically, the tumour was positive for human melanoma black 45 (HMB-45) and vimentin but negative for S-100 and Melan-A." (PMID 28086809, 2017). "Our findings revealed that CD24br cells showed slightly elevated level of VIM, a marker for cells undergoing EMT, and larger tumour growth that was not as marked as compared to other bright phenotypes." (PMID 28959019, 2017). "The pairwise comparisons of Snail, Twist, E-cadherin, N-cadherin, and Vimentin expression between TSCC and corresponding tumor adjacent normal tissues." (PMID 28570699, 2017). "The Mes‐Inf tumours were negative for a large number of basal cell‐related and SCC‐related cytokeratins, but positive for tumour‐cell expression (IHC) of both ZEB2 and VIM." (PMID 28195647, 2017). "On immunohistochemical (IHC) examination, the sarcoma tumor cells were stained positive for CD34, CD31, vimentin, CD68, Calponin, F8 and Ki67 (80%), while negative for Bcl-2, Desmin, EMA, SMA, CK and ALK-1." (PMID 29113426, 2017). "Tumor cells also had heterogeneous cytoplasmic staining positive for WT1 and negative for vimentin and α-sma antibodies (data not shown)." (PMID 28845162, 2017). "On IHC (immunohistochemistry), the tumor cells were negative for GFAP, CK, HMB-45 and showed diffuse positivity for D2-40 and vimentin." (PMID 28860959, 2017). "Per report, the tumor exhibited weak and focal positivity for CD117 (KIT), vimentin and calretinen, and was negative for SMA, S100, CD34, and desmin." (PMID 28768491, 2017). "The immunophenotype (AE1/AE3-, vimentin+, PAX8-, alpha-inhibin+, Melan-A+, synaptophysin+ and NSE+) did not support a renal origin of the tumor." (PMID 27094262, 2016). "The tumor cells immunestained was positive for HMB-45, focally positive for c-Kit (CD117), and negative for vimentin, S-100, AE1/AE3, CK-7, CK-18, CD-10, RCC antigen, CgA, DOG-1, EMA, smooth muscle actin, and synaptophysin." (PMID 27858882, 2016). "Immunohistochemistry showed the tumour cells to strongly express PAX8, Vimentin, CAM5.2, AMACR and EMA, focal E-cadherin expression with no tumour expression of CD10, RCCAg, CK7, or CD117." (PMID 27005674, 2016). "By immunohistochemical examination, the tumor was strongly positive for HMB-45, focally positive for c-Kit (CD117), and negative for vimentin, S-100, AE1/AE3, CK-7, CK-18, CD-10, RCC antigen, CgA, DOG-1, EMA, smooth muscle actin (SMA), and synaptophysin." (PMID 27858882, 2016).